PRDM2 (PR/SET domain 2)
Diseases named in the same sentence as PRDM2 in open-access papers (continued):
Sharing a sentence is not in itself a finding about the gene and the disease.
tumor (62 papers, 2001 to 2025). "Reduced PRDM2 expression is associated with dopamine–agonist resistance and tumor recurrence in prolactinomas." (PMID 40867614, 2025). "The tumour suppressor gene PRDM2 harboured frameshift mutations on the trunks of Tumours 2 and 3 and a second frameshift mutation was acquired in subclones of each tumour, potentially leading to biallelic inactivation." (PMID 31949146, 2020). "Using this model we demonstrate for the first time that the c.4467delA frameshift mutation in PRDM2 leads to deregulated growth and increases the malignant potential of human tumor cells." (PMID 29228717, 2017). "Bearing in mind its proposed tumor suppressor role, correction of one PRDM2 allele in HCT116 should be sufficient to restore the PRDM2 protein function that is lost due to truncation." (PMID 29228717, 2017). "The chromatin modifier PRDM2/RIZ1 is inactivated by mutation in several forms of cancer and is a putative tumor suppressor gene." (PMID 29228717, 2017). "Both SETD8 binding domain and methyltransferase activity are essential for PRDM2 tumor suppressor function, and frameshift mutations resulting in a truncated protein incapable of binding SETD8 are a frequent hallmark of various aggressive cancers." (PMID 27688818, 2016). "PRDM2 showed a synergistic effect with BRC on the inhibition of prolactin (PRL) secretion and MMQ cell viability, and low PRDM2 expression was associated with tumor recurrence." (PMID 25884948, 2015). "In all these tumor types, the tumor tissue samples and cancer cell lines displayed low expression levels or deficiency of PRDM2." (PMID 25884948, 2015). "The low expression of PRDMs could be linked to enhanced immune surveillance, as PRDM2 expression might affect the immunogenicity of tumor cells." (PMID 39468462, 2024). "We detected the germline variants of RECQL4, CNTNAP2, and PRDM2, which are tumor suppressor genes." (PMID 36975488, 2023). "In addition, we found that subgroup meta-analysis by geographical populations showed p16, RUNX3 and PRDM2 hypermethylation was a common risk factor between HCC tumor tissues and normal tissues in HCC patients." (PMID 27835605, 2016). "Furthermore, binary multivariate regression revealed that low levels of PRDM2 mRNA were independently associated with tumor recurrence (odd ratio [OR] 0.065, 95% confidence interval [CI]: 0.05–0.832, p = 0.036)." (PMID 25884948, 2015). "Studies suggest that PRDM2 also plays a potential tumor-suppressor role in testicular germ–cell tumor formation." (PMID 40867614, 2025). "In conclusion, promoter hypermethylation of the PRDM2/RIZ gene leads to transcriptional silencing of the tumor-suppressive isoform RIZ1, thereby altering its biological functions and contributing to carcinogenesis in major digestive system organs." (PMID 40867614, 2025). "Noteworthy, PRMT2 was recently reported to be induced and contribute to HCC tumorigenesis, DIDO1 has been involved in numerous types of tumors, and PRDM2 is a tumor suppressor epigenetically repressed in HCC." (PMID 37620598, 2023). "As truncated PRDM2 has been suggested to have a compromised tumor suppressor function, the growth properties of the three PRDM2insG clones were compared to parental cells." (PMID 29228717, 2017). "The tumor suppressor role of PRDM2 has previously been suggested based on several lines of evidence." (PMID 29228717, 2017). "Restored PRDM2 increased global histone 3 lysine 9 dimethylation and reduced migration, anchorage-independent growth and tumor growth in vivo." (PMID 29228717, 2017). "Rice and coworkers reported a specific and direct binding of SETD8 with the Riz1/PRDM2/KMT8 tumor suppressor and showed that the N-terminal domain of PRDM2 preferentially monomethylates H3K9, thus establishing a H4K20me1-H3K9me1 trans-tail “histone code”." (PMID 27688818, 2016). "Subgroup meta-analysis by geographical populations was performed for p16, RASSF1A, GSTP1, APC, RUNX3, SOCS1 and PRDM2 between HCC tumor tissues and adjacent tissues." (PMID 27835605, 2016).
tumor (continued). "The subgroup meta-analysis by geographical populations was also performed for p16, APC, RUNX3 and PRDM2 between HCC tumor tissues and normal tissues." (PMID 27835605, 2016). "Further work will be required to extend the potential links between PRDM2, drug resistance and tumor recurrence." (PMID 25884948, 2015). "As a new tumor suppressor, PRDM2 has been analyzed in a few reports, which have attempted to explain the reasons the gene is inactivated in cancer cells." (PMID 25884948, 2015). "Here we show that PR-Set7 specifically and directly binds the C-terminus of the Riz1/PRDM2/KMT8 tumor suppressor and demonstrate that the N-terminal PR/SET domain of Riz1 preferentially monomethylates H3K9." (PMID 24423864, 2014). "PRDM2 (RIZ1) is the first identified member of methyltransferase family with tumor suppressive function mediated by its PR domain." (PMID 22087297, 2011). "We have previously proposed that methyl-balanced diet prevents cancer by activating the histone lysine methyltransferase (KMT) class tumor suppressors such as RIZ1 (PRDM2 or KMT8)." (PMID 18852888, 2008). "While RIZ1 is generally considered a tumor suppressor, some findings may reflect the mixed or ambiguous effects of PRDM2 isoforms in specific contexts." (PMID 40867614, 2025). "PRDM2 is involved in tumor suppression, and its expression is often silenced in many cancer types." (PMID 36975488, 2023). "For effective PRDM2/RIZ1 tumor suppressor activity, the PR-binding motif is required." (PMID 32290321, 2020). "Taken together, our findings indicate that RIZ2 upregulation may contribute to tumor promotion, supporting the hypothetical oncogenic role of this PRDM2 protein isoform." (PMID 33585202, 2020). "PRDM2 is localized in a chromosome region (1p36), which is commonly affected by genetic alterations in a broad range of human malignancies thus suggesting a tumor-suppressor role for this gene (and references therein)." (PMID 32290321, 2020). "Therefore, PRDM2 is actually considered a candidate tumor suppressor gene in different types of cancer." (PMID 27983647, 2016). "In summary, our results suggest that low levels of PRDM2 may contribute to promote drug resistance and tumor recurrence of prolactinomas in an as yet unknown manner." (PMID 25884948, 2015). "PRDM2 downregulation may play a role in dopamine-agonist resistance and tumor recurrence in prolactinomas." (PMID 25884948, 2015). "The PRDM2 gene is one of the candidate tumor suppressor genes on chromosome 1p." (PMID 25884948, 2015). "For example, RIZ1, the full-length product of PRDM2, is a tumour suppressor protein because it demonstrates a loss of function in many types of human cancers with genomic deletions or point mutations and because RIZ1-deficient mice have been shown to develop diffuse large B cell lymphomas (DLBCL)." (PMID 25436766, 2012). "This could be explained by the participation of the retinoblastoma protein-interacting zinc finger protein (RIZ) or positive regulatory domain methyl transferase (PRDM2), which has tumor-suppressive capabilities, in the process of erythropoiesis, which may also involve the RB gene." (PMID 38024824, 2023). "Thus, the restoration of one allele of PRDM2 in HCT116 cells has a negative impact on tumor cell growth and invasiveness." (PMID 29228717, 2017). "Regarding histone modifications, it has been stated that non-invasive PitNETs express higher amounts of the anti-PRDM2 antibody (RIZ1), acting as tumor suppressors and as histone methyltransferase in comparison to invasive PitNETs." (PMID 40299639, 2025). "The PRDM protein family, including members such as PRDM2 and PRDM16, showcases a similar yin-yang paradigm in tumor contents observed in PRDM1, characterized by two functionally antagonistic isoforms originating from a single gene." (PMID 39562537, 2024).
tumor (continued). "Noteworthy, several reports indicated that PRDM2/RIZ1 is endowed with tumor suppressor activities, whereas PRDM2/RIZ2 acts as an oncogene with putative intrinsic growth-promoting properties." (PMID 36964555, 2023). "Several PKMTs, including MLL3, PRDM2/RIZ, PRDM5, SMYD4, SUV4-20H2, and EEF1AKMT3, have been reported to exhibit tumor suppressor activities." (PMID 38036730, 2023). "These include alterations in e.g. MSH4, PRDM2, and TP53I3 in the MSI tumor as well as GATA, DOCK5, and IGSF11 in the MSS tumor." (PMID 28683819, 2017). "The meta-analysis of p14, p15, p73, APC, SOCS1, MGMT, SFRP1, PRDM2, DAPK1, RARβ, IGF2 and hMLH1 genes methylation was performed between HCC tumor tissues vs adjacent tissues and HCC tumor tissues vs normal tissues." (PMID 27835605, 2016). "PRDM2 is a member of the PRDM (PRDI-BF1 and RIZ domain containing) family, one member of which, PRDM5, down-regulates MDM2 gene expression to inhibit tumor cell clonogenicity and cell proliferation." (PMID 24124579, 2013). "Several tumour suppressor genes (BAI3, PEG3, PRDM2, RB1CC1) along with the natural killer receptor KLRC1 were also down regulated in BAT." (PMID 23472076, 2013). "Among the MNA tumors (n=10), five tumor suppressor genes (among other genes) were underexpressed within the distal 1p: CAMTA1, KIF1B, PRDM2, FABP3, and CDKN2C; whereas MYCNOS and MYCN were the two top differentially upregulated genes on 2p." (PMID 23656755, 2013). "Among the genes differentially methylated are number of well- known tumor suppressor genes, namely RASSF1, DLG1, DLC1 and PRDM2, as well as various other tumor related genes." (PMID 24212793, 2011). "Taken together, these data suggest that AEP-specific cleavage of DDX3X leads to nuclear translocation and that nuclear tDDX3X-C regulates oncogenic splicing in multiple kinds of malignant tumors, especially via PRDM2 and ARRB1, under tumor microenvironmental stimuli dependent on HIF1A." (PMID 37988165, 2023). "AEP/tDDX3x–induced PRDM2-Δexon 2 and ARRB1-Δexon 13 promote tumor malignancy." (PMID 37988165, 2023). "While some such as PRDM2 and PRDM5 act as tumor suppressors, PRDM14 appears to be an oncogene." (PMID 31143550, 2019). "In conclusion, we identified novel recurrently mutated genes in T-PLL, including PTPRC, regulating the JAK/STAT pathway, epigenetic regulators like PRDM2 and HERC1/2, and genes involved in DNA damage response and DNA repair like SAMHD1, which has most likely a tumor-suppressor function in T-PLL." (PMID 29352181, 2018).
cancer (39 papers, 2007 to 2025). A tumor composed of atypical neoplastic, often pleomorphic cells that invade other tissues. "Proliferation-related assays, including Cell Counting Kit-8 (CCK-8) and colony formation assays, were performed, and as expected, loss of PRDM2 or gain of the ARRB1-Δexon 13 isoform induced by AEP/tDDX3X-C promoted cancer cell proliferation." (PMID 37988165, 2023). "Using variants of the keywords “PRDM2” and “cancer”, we performed a search from inception to July 2019 in PubMed, Cochrane Library, ProQuest, EBSCO and ScienceDirect." (PMID 32391195, 2020). "For instance, frameshift mutations of microsatellite repeats within the PRDM2 coding region are frequent events in various cancers." (PMID 30347759, 2018). "Loss of 1p36, epigenetic silencing or inactivating mutations within the PRDM2 PR domain are observed in many cancer types." (PMID 29228717, 2017). "Moreover, we observed a 2-fold decrease in the in vivo growth rate of PRDM2insG xenografts, demonstrating that loss of PRDM2 contributes to a more aggressive cancer phenotype." (PMID 29228717, 2017). "PR structural domain-containing 2 (PRDM2) is in the chromosomal region (1p36), and this region is commonly influenced by genetic alterations in a variety of malignant tumors." (PMID 40867614, 2025). "Specifically, PRDM2 gene is often target of aberrant DNA methylation and frameshift mutations in CRC; besides, most of the identified PRDM2 mutations were enriched in cancers exhibiting MSI." (PMID 37853459, 2023). "Another alternatively spliced gene revealed in our study, PRDM2, is a tumor suppressor gene, downregulated in various cancers." (PMID 37894381, 2023). "Mechanistically, the role of PRDM2 products in cancer can be explained partly through its known functions." (PMID 32290321, 2020). "Genetic or epigenetic modifications of the PRDM2/RIZ gene observed in human cancers lead to silencing of RIZ1 expression, while, in contrast, they do not affect RIZ2 expression level." (PMID 33585202, 2020). "Overall, PRDM2, PRDM3/MECOM, PRDM9, PRDM16 and ZFPM2/FOG2 were the most mutated genes with pan-cancer frequencies of protein-affecting mutations higher than 1%." (PMID 30347759, 2018). "Several of the EMT genes identified by us as putative PRDM2 targets have been previously shown to be overexpressed in several cancer types." (PMID 29228717, 2017). "The downregulation of such genes observed here suggests that restoration of PRDM2 H3K9me2 activity leads to transcriptional repression of genes involved in EMT and diminishes the cancer associated phenotypes of parental HCT116 cells." (PMID 29228717, 2017). "Taken together, PRDM2 expression was maintained in cancer cell lines, suggesting that probably in tumors the mechanism of action of RIZ proteins is modified." (PMID 27983647, 2016). "We also observed somatic variants in several known cancer-associated genes (for example, JAG1, PRDM2, PRDM8, SETD2, ASPM, ZIC, GRIK1, etc.), which may be important for cell growth and proliferation." (PMID 30871634, 2019). "In the unclassified subgroup, apart from previously reported mutations in epigenetic regulators in multiple cancers, including KMT2C, KMT2D, KMT2B, PRDM2, NCOR2, KAT6B, and EP300, in this cohort, we also found new recurrent mutations in epigenetic regulators, including CREBBP and PRDM16." (PMID 30950204, 2019). "In both GC-1 mouse spermatogonial normal cell line and in TCam-2 human spermatogonial cancer cell line (respectively), treatment with proliferation-inducing agents modulated the relative ratio between the major transcripts coded by PRDM2 gene." (PMID 27983647, 2016). "To determine the effects of PRDM2-Δexon 2 and ARRB1-Δexon 13 isoforms on cancer cell function, we performed rescue experiments using the following groups of cancer cells: NC, AEP KD, AEP KD/tDDX3X-C res, AEP KD/PRDM2 KD, and AEP KD/ARRB1-Δexon 13 res cells." (PMID 37988165, 2023).
cancer (continued). "A potential role for PRDM10 in cancer is to be highly expected since several better studied members of the PRDM family, PRDM2, PRDM3, PRDM5, and PRDM14, are known to play an important role in a variety of cancers." (PMID 31143550, 2019). "However, the mRNA expression levels of PRDM1, PRDM2, PRDM8, and PRDM11 were higher in normal and cancer tissues." (PMID 39468462, 2024). "Thus, AEP promoted oncogenic splicing of widespread pre-mRNAs via tDDX3X-C, and the PRDM2-Δexon 2 and ARRB1-Δexon 13 isoforms induced by AEP/tDDX3x promote cancer cell proliferation." (PMID 37988165, 2023). "Although genetic inactivation, epigenetic silencing, chromosomal deletion, or alternative use of different promoters has been frequently revealed in several cancers, the AS event of PRDM2 has not been reported." (PMID 37988165, 2023). "Despite their high prevalence the functional significance of PRDM2 C-terminal truncating mutations in CRC and cancer in general has not been clarified." (PMID 29228717, 2017). "In addition to its frequent inactivation in different cancer types, the increased incidence of a broad spectrum of tumors in PRDM2/RIZ1 KO mice and impaired tumorigenicity in nude mice following overexpression of PRDM2/RIZ1 are indicative of this." (PMID 29228717, 2017).
bacterial infection (2 papers, 2020 to 2021). "Also, the PRDM2 gene was referred to play a role in resistance to disease and bacterial infection or cell-mediated immune response, especially paratuberculosis resistance in ruminants." (PMID 34253178, 2021). "The four CHIA, CHI3L2, PRDM2 and KDM5B genes that we identified on BTA4 and 16 in the Swedish Red Cattle were previously reported as disease resistance genes (i.e. to gastrointestinal nematodes or bacterial infection) in independent studies on sheep and cattle breeds." (PMID 32887549, 2020).
bladder (2 papers, 2018 to 2019). "Our meta-analysis was unable to find any statistical significance between HBV-positive carcinoma tissues and HBV-negative carcinoma tissues for the methylation of the remaining seven genes, including RUNX3, p14, WIF1, CDH1, PRDM2, SOCS1 and MGMT." (PMID 31772678, 2019). "The meta-analysis of p14, WIF1, PRDM2, p15 and MGMT gene methylation was performed between HBV-positive carcinoma tissues and HBV-negative carcinoma tissues." (PMID 31772678, 2019).
infection (1 paper, 2019). The state of being infected such as from the introduction of a foreign agent such as serum, vaccine, antigenic substance or organism. "HDAC5, KDM2B, EZH1, PRDM2, SETMAR, SMYD4 and USP12 were differentially expressed at all time points post-infection (excluding 2 hpi)." (PMID 30728374, 2019).
infectious disease (1 paper, 2025). A disorder directly resulting from the presence and activity of a microbial, viral, or parasitic agent in humans. "Further mechanistic exploration of PRDM2 in immune modulation and inflammatory signaling may expand its relevance to autoimmune and infectious diseases." (PMID 40867614, 2025).
neurodegenerative disease (1 paper, 2020). A disorder of the central nervous system characterized by gradual and progressive loss of neural tissue and neurologic function. "The TF genes FSOL2, MESI2, NEF2L2, and PRDM2 have been reported to be associated with neurodegenerative diseases." (PMID 32149119, 2020).
PRDM2 also shares sentences with these, for which no sentence is quoted: cervical cancer (6 papers); neuroblastoma (6); ovarian carcinoma (6); chronic myeloid leukemia (5); liver cancer (5); colon cancer (4); endometrial cancer (4); esophageal squamous cell carcinoma (3); glioblastoma (3); leukemia (3); stomach cancer (3); cardiovascular diseases (2); chromaffin tumor (2); esophageal cancer (2); hematological cancers (2); malignant meningioma (2); seminoma (2); acute lymphoblastic leukaemia (1); acute myeloid leukemia (1); alcohol use disorders (1); anxiety disorder (1); benign neoplasm (1); Cirrhosis (1); depression (1); diabetes (1); endometrial adenocarcinoma (1); familial melanoma (1); germ cell tumor (1); liver fibrosis (1); liver neoplasm (1).
A further 19 diseases each share a sentence with PRDM2 in 1 paper.